ZNF229 (zinc finger protein 229)
Description:
May be involved in transcriptional regulation.
Tractability: PROTAC: UniProt records ubiquitination sites on it; ubiquitination databases record sites on it.
Gene: Protein-coding gene on chromosome 19 (44,417,519 to 44,448,578, reverse strand). Ensembl gene ENSG00000278318.
Subcellular location: Nucleus
Subcellular location (Human Protein Atlas): Vesicles; Plasma membrane
Gene Ontology:
Molecular function: protein binding; transcription cis-regulatory region binding
Biological process: regulation of transcription by RNA polymerase II; regulation of DNA-templated transcription
Cellular component: nucleus
Genetic constraint (gnomAD): Loss-of-function variants: 9 observed, 11.89 expected, observed/expected ratio (o/e) 0.76, 90% interval 0.46 to 1.32. The upper end of that interval is the gene's LOEUF score, 1.32, which puts it in group 5 of 6, group 1 being the genes least tolerant of losing a copy. Missense variants: 1,043 observed, 1,067 expected, observed/expected ratio (o/e) 0.98, 90% interval 0.93 to 1.03. Synonymous variants: 368 observed, 387.4 expected, observed/expected ratio (o/e) 0.95, 90% interval 0.87 to 1.04.
Homologues: Orthologues: chimpanzee ZNF229 (97% identical), dog ZNF229 (76% identical). Paralogues in human: ZNF112 (43% identical), ZNF226 (39% identical), ZNF234 (37% identical), ZNF235 (36% identical), ZNF227 (35% identical), ZNF33B (35% identical), ZNF45 (35% identical), ZNF224 (35% identical), ZNF658 (35% identical), ZNF28 (34% identical), ZNF841 (34% identical), ZNF41 (33% identical), and 164 more.
Diseases named in the same sentence as ZNF229 in open-access papers:
ZNF229 is named in the same sentence as 4 diseases in open-access papers, as found by Europe PMC text mining. Sharing a sentence is not in itself a finding about the gene and the disease. The quoted sentences say what the papers report.
leukemia (1 paper, 2021). A malignant (clonal) hematologic disorder, involving hematopoietic stem cells and characterized by the presence of primitive or atypical myeloid or lymphoid cells in the bone marrow and the blood. "Among the other genes with strong correlations between DNA methylation and gene expression, aberrant DNA methylation and downregulation of FKBP9, CA8, MSC, TRPC6, ZNF492, ZNF229, and ZNF471 genes in leukemia patients are reported here for the first time." (PMID 34575904, 2021).
tuberculosis (1 paper, 2012). A chronic, recurrent infection caused by the bacterium Mycobacterium tuberculosis. "Interestingly, ZNF229 is associated with tuberculosis resistance, and the prevalence of tuberculosis is low among Qataris." (PMID 23139751, 2012).
cancer (2 papers, 2021 to 2022). A tumor composed of atypical neoplastic, often pleomorphic cells that invade other tissues. "ZNF229 is a protein-coding gene, and few studies have suggested the hypermethylation status of ZNF229 in cancer diagnosis." (PMID 34778269, 2021).
ZNF229 also shares sentences with these, for which no sentence is quoted: cervical cancer (1 paper).